IDO1 (indoleamine 2,3-dioxygenase 1)
Diseases named in the same sentence as IDO1 in open-access papers (continued):
Sharing a sentence is not in itself a finding about the gene and the disease.
cancer (continued). "Future directions in targeting the kynurenine pathway include the development of dual inhibitors that target both IDO1 and TDO2, as well as the investigation of combination therapies that include metabolic inhibitors, ROS inducers, and other agents that disrupt cancer metabolism." (PMID 39997327, 2025). "IDO1 expression has been reported in cancer cells and in the stroma surrounding the tumor microenvironment (TME) (e.g., endothelial cells, fibroblasts, immune cells, and mesenchymal cells), as well as in peripheral blood mononuclear cells of cancer patients." (PMID 40848064, 2025). "Clinical outcome analyses reveal that elevated tumoral IDO1 expression or increased serum Kyn/Trp ratio correlates with reduced progression-free survival across multiple cancer types, independent of other prognostic factors." (PMID 40894232, 2025). "Currently, the primary clinical treatments include inhibitors targeting different enzymes in the kynurenine pathway, such as IDO1 inhibitors, TDO inhibitors, and KMO inhibitors, which have shown efficacy in cancer, immune diseases, neurological diseases, and neurodegenerative diseases." (PMID 39940736, 2025). "Several pharmacological strategies are currently under investigation, including indoleamine 2,3-dioxygenase 1 (IDO1) inhibitors, kynurenine 3-monooxygenase (KMO) inhibitors, and tryptophan mimetics, primarily in the context of cancer, neurodegeneration, and chronic inflammatory diseases." (PMID 40426950, 2025). "Altogether, the data indicate that IDO1 catalytic inhibitors sustained the expression of a non-enzymatic conformation of IDO1 in the FTC-133 cancer cell line through a post-translational mechanism that prolongs its protein half-life." (PMID 41262240, 2025). "We found that MSCs had reduced levels of IDO1 compared to iPSC and cancer cell line populations, although this was not significant." (PMID 39621192, 2025). "Furthermore, IDO1 and Kyn pathway metabolites activate PI3K‐Akt signaling cascade in neoplastic colonic epithelial cells, promoting cancer cell proliferation and inhibiting apoptosis." (PMID 41332472, 2025). "Therefore, a metal matrix protease-2 (MMP-2) and endogenous GSH dual-responsive liposomal-based nanovesicle, co-loading with 5-FU (anti-cancer drug) and NLG919 (IDO1 inhibitor), was constructed (named as ENP919@5-FU)." (PMID 38755645, 2024). "The effect of Trp‐catabolizing enzyme IDO1 on glycolysis in cancers has not been explored and warrants clarification." (PMID 38706741, 2024). "However, it was a favorable factor in the six cancers (HNSC, MESO, OV, READ, SARC, and SKCM) where IDO1 expression was high, and gene expression was negatively correlated with survival." (PMID 38539263, 2024). "Altogether, current data suggest that IDO1 is not a suitable prognostic marker for HNSCC patient survival or for cancer recurrence." (PMID 38736462, 2024). "Additionally, to better understand the connection between IDO1 and immunity, we used three methods to measure immune cells in the TME in pan-cancer, including EPIC, QUANTISEQ, MCP-counter." (PMID 38539263, 2024). "Like IDO1, TDO2 is expressed at higher levels in cancer tissue than in normal tissue." (PMID 39272943, 2024). "The multifaceted role of IDO1 in CRC, from immune tolerance and prognostic implications to intricate molecular pathways and potential therapeutic interventions, underscores the complexity of this enzyme in the context of cancer biology." (PMID 38646539, 2024). "The model recapitulates an aggressive and typically intractable cancer, so it is perhaps not surprising that IDO1/TDO2 inhibition alone does not confer a positive disease outcome." (PMID 39048947, 2024). "IDO1-positive carcinomas (n = 90): Negative immunostaining for ER-α was detected in 72 carcinomas (80%), whereas 18 (20%) stained positive for ER-α." (PMID 39061522, 2024). "IDO1-negative carcinomas (n = 6): The histotypes were tubular (n = 3), tubular and solid (n = 2), and solid (n = 1)." (PMID 39061522, 2024).
cancer (continued). "While most of the preceding points refer to IDO1, the relative expression of IDO1 or IDO2 and that of PD-L1 or PD-L2 may have a strong influence on cancer outcome." (PMID 37296860, 2023). "Increasing attention is being given to IDO2 as a potential alternative anti-cancer target when IDO1 inhibition is not effective." (PMID 37296860, 2023). "An NLG919-mediated inhibition of IDO1 in the NLG/Oxa (IV), liposomes can effectively prevent the depletion of tryptophan to immunosuppressive kynurenine in cancer cells, as well as release the cytotoxic oxaliplatin into the cytosol to induce immunogenic cell death (ICD)." (PMID 37427139, 2023). "IDO1 inhibitors were developed and tested in numerous cancer clinical settings without knowledge of the overlapping pathways regulated by IL4i1, and without knowing that both IDO1 and IL4i1 control redox stress responses." (PMID 37196768, 2023). "The shift towards selective inhibitors of IDO2, dual inhibitors of IDO1 and IDO2 or dual inhibitors of IDO1/2 and TDO represents a sensible trend toward a definitive assessment of the value of dioxygenase inhibition in cancer." (PMID 37296860, 2023). "Moreover, IDO1 and IDO2 have been considered to possess different abilities in anti-cancer immunity regulation." (PMID 36765782, 2023). "In some cancer cell types, TDO2 and IDO1 expression can also be uncoupled from the regulatory signals that control enzyme expression in immune cells: We discuss this aspect briefly as a counterpoint to the immune functions of arginine and tryptophan metabolism." (PMID 37196768, 2023). "Therefore, IDO1 and TDO, which enable cancer cells to escape from immunologically mediated rejection, become the attractive targets for the development of inhibitors." (PMID 37564938, 2023). "In addition, the Trp-degrading enzyme indoleamine-2,3-dioxygenase 1 (IDO1), which is a widely expressed and interferon-inducible enzyme, produces kynurenine (KYN) and is highly expressed in multiple types of human cancers, including GBM." (PMID 36986469, 2023). "Additionally, screening for the expression of drug targets in brain metastasis of both cancers revealed a high level of VISTA and IDO1 in BM-LUAD, with relatively higher expression of VISTA compared to IDO1." (PMID 37061716, 2023). "Overall, these findings provided evidence that the dual inhibitors of IDO1 and STAT3 may offer a promising avenue for the development of highly effective drug candidates for cancer therapy." (PMID 37630387, 2023). "Moreover, correlation analysis hinted at a negative correlation of TMEM59L expression with CD8 T cells, activated CD4 T cells, and several immunomodulators, including IDO1, TIGIT, PD-L1, CTLA-4, and BTLA in various cancers." (PMID 36618425, 2022). "IDO1, in combination with other immunotherapeutics such as PD-1/PD-L1 or CTLA-4 inhibitors, has an objective response rate that varies between 10% and 57% in different cancer types." (PMID 35903691, 2022). "Moreover, the link between tryptophan metabolism pathways and cancer has prompted a lot of researches on treatments targeting the kynurenine pathway, especially by inhibiting the key enzymes including TDO, IDO1 and KMO." (PMID 35494045, 2022). "To date, the evaluation of IDO1 inhibitors alone or combined with ICI in clinical trials have provided disillusioning results, requiring more comprehensive understandings on the role of Trp-Kyn-AhR pathway in cancer development and immunology." (PMID 35173722, 2022). "Recombinant ASPN induced expression of KYNU and IDO‐1 within several hours in NFs, while they were not induced by CM derived from at least other two cancer cells." (PMID 34379869, 2022).
cancer (continued). "The indoleamine 2,3-dioxygenase 1 (IDO1) metabolic circuitry, comprising the first tryptophan (Trp) catabolite L-kynurenine (Kyn) and the aryl hydrocarbon receptor (AHR), has emerged as a mechanism of cancer immune evasion." (PMID 35371054, 2022). "Moreover, correlation between KIF15 and immune gene set was analyzed, and the expression of several important immune-related genes was significantly related to KIF15 expression level in pan-cancer, such as CTLA4, IDO1, and LAG3." (PMID 35359374, 2022). "Research on IDO1 activity in cancer has focused predominantly on the concept that TRP depletion is the main regulatory node of T cell suppression, which spurred the development of IDO1 inhibitors and their testing in clinical cancer settings." (PMID 35245456, 2022). "Clinical trials are suggested to test the efficacy of combinatory therapy of IDO1 inhibitor and PD1/PD-L1 blockade in treating smoker patients with high level of IDO1, which may probably revive IDO1 inhibitor for cancers." (PMID 36068203, 2022). "Based on this study, the participation of components of the kynurenine pathway downstream of IDO1/TDO is highlighted, since they may be potential therapeutic targets that contribute to immunotherapy in cancer." (PMID 36355137, 2022). "Nowadays, cancer immunotherapy includes approaches such as immuno-binding site-blocking therapy, adoptive immunotherapy, indoleamine 2, 3-dioxygenase 1 (IDO1) inhibitors, cancer vaccines, and nonspecific immunomodulators." (PMID 35463305, 2022). "Overexpression of IDO1 is considered a negative prognostic marker in several cancer types, including PC." (PMID 35406118, 2022). "Overall, targeting IDO1 not only in immune cells but also in cancer cells could be a beneficial therapeutic strategy for PDAC and potentially for other cancers as well and that carbidopa could be repurposed to treat cancers that overexpress IDO1." (PMID 35997090, 2022). "These latter authors also reported TDO2 expression in intratumoral pericytes of most cancers and confirmed the absence of co-expression of IDO1 and TDO2 in glioblastoma that can be deduced from other data." (PMID 36286592, 2022). "Potent IDO1 inhibitors have been discovered for decades, whereas no clinical drugs are used for cancer treatment up to now." (PMID 35563059, 2022). "The IDO1 paralog IDO2, despite having received far less research, may be a possible alternative as a therapeutic target in cancer immunotherapy." (PMID 36551617, 2022). "Ido1-expressing Paneth-like cancer cells were almost absent in Tyk2Δ/Δ tumors and expression of antigen presentation machinery genes was reduced." (PMID 36185806, 2022). "Additionally, two trials studied inhibitors of indoleamine 2,3-dioxygenase 1 (IDO1), an enzyme that catalyzes the oxidation of L-tryptophan achieving metabolic modulation in multiple immune pathways in the cancer microenvironment." (PMID 36358601, 2022). "The CAFDL signature was significantly positively associated with TGFB1, CD276, CD40, VEGFA, VEGFB, etc., but showed significantly negative correlation with immune checkpoints (such as CD274, PDCD1, CTLA4, TIGHT, and HAVCR2) and anti-cancer immune regulators (IFNG, IDO1, and GZMA)." (PMID 35967425, 2022). "In addition, we studied the relationship between the expression of KCC2 (SLC12A5) and NKCC1 (SLC12A2) in pan-cancer and immune checkpoint genes, including SIGLEC15, IDO1, CD274, HAVCR2, PDCD1, CTLA4, LAG3, and PDCD1LG2." (PMID 35372048, 2022). "The present findings have highlighted a previously unknown role of IDO1 other than immunosuppressive activity in HCC, which may be applicable to other cancer types." (PMID 34769098, 2021). "A few IDO1 inhibitors have been reported, some of which, including epacadostat, BMS986205, indoximod, and PF-06840003, among others, have advanced into clinical trials for cancer treatment." (PMID 34681715, 2021).
cancer (continued). "Publicly available data (The Human Protein Atlas) shows several examples of human PDAC tumors with strong IDO1 expression, and that IDO1 is primarily confined to cancer cells rather than stromal cells." (PMID 33831358, 2021). "Still, the high activity of IDO1, and thus a decreased TRP level leads to abnormal activity of immunosuppressive Tregs, whose pro-tumorigenic activity is based on crosstalk with other immune cells, as well as on a direct impact on cancer cells." (PMID 34071442, 2021). "CD8A expression is correlated with all three genes in 22 cancer types, and with IDO-1 and IDO-2 (but not TDO-2) in nine more cancer types, so CD8+ T-cell infiltration is likely a widespread predictor of IDO pathway over-expression." (PMID 34367262, 2021). "Increased expression of IDO1 correlates with a decreased level of infiltrating CD3+ T-cells, CD8+ T-cells, CD57+ NK-cells, B-cells, and increased level of Foxp3+ Treg in various types of malignant tumors." (PMID 34943606, 2021). "In fact, the consumption of Trp and the accumulation of Kyn do not always happen simultaneously in human cancers, and the immunosuppression effects of IDO1 in TME do not just depend on its enzyme activity." (PMID 35003126, 2021). "In metastatic uveal melanoma, TDO2 but not IDO1 was found to be expressed in cancer tissue, in a constitutive manner." (PMID 34071442, 2021). "However, the available data indicate that the expression level of IDO1, IDO2 and TDO2 differs between cancer types and that the occurrence of each enzyme alone can be an independent prognosis factor." (PMID 34071442, 2021). "The available evidences support that IDO1, TDO, and IDO2 may be all involved in malignant tumor, but the three differ in the expression, regulatory mechanism, and the role in different TME." (PMID 35003126, 2021). "Conversely, (D-)2HG and IDO1/TDO2-related metabolites tryptophan and kynurenine are two examples of the successful application of LC-MS-based technology to assess metabolites as biomarkers in cancer." (PMID 34203535, 2021). "In our study, IDO1 staining was observed only in some cancer tissues and in some noncancer ones as well, which is in agreement with the previous reports." (PMID 33922995, 2021). "IDO1 regulates peripheral immunity and is induced by pro-inflammatory molecules including type I and II interferons, TNF-α, lipopolysaccharide, and prostaglandin E in a wide range of cells including myeloid cells, fibroblasts, and cancer cells." (PMID 33708223, 2021). "Due to the uncertain benefit of IDO1 inhibition as a strategy to enhance immune checkpoints activity, and since approximately 35% of tumor cancer cell lines express TDO, this enzyme became a very attractive target in cancer immunotherapy." (PMID 33806305, 2021). "The endometrial cells derived from cancer and noncancerous tissue were fixed on chamber slides and stained with anti-IDO1 antibody to observe protein expression." (PMID 33922995, 2021). "However, it was also positively correlated with multiple inhibitory checkpoint molecules (IDO1, IDO2, and KIR3DL1) in multiple cancer types." (PMID 34234847, 2021). "Most of the cells present in the tested cultures were found positive for IDO1 in IF, despite being derived from cancer or noncancerous tissue." (PMID 33922995, 2021). "Despite a rich literature addressing how IDO1-driven tryptophan metabolism affects the behavior of immune cells, knowledge of how this pathway influences metabolic pathways within cancer cells themselves is largely absent." (PMID 33831358, 2021).
cancer (continued). "The smoking parameter appeared to be not related to Trp catabolism in our analysis, although a decreased serum activity of the IDO1 enzyme had been documented in a study on a representative cohort of smoking subjects not affected by cancer." (PMID 33922388, 2021). "So far, five IDO1 inhibitors were studied as potential therapeutic options in cancer patients: indoximod [IDO pathway modulator; 1-methyl-D-tryptophan (1-MT)], epacadostat (selective IDO1 inhibitor; INCB024360), navoximod (GDC-0919), BMS-986205, and IDO1-targeting vaccines." (PMID 32153576, 2020). "Recent studies indicated a promising therapeutic efficiency in cancer with a silencing approach for intracellular negative immune regulators in tumors, i.e., IDO1, PD-1 or PD-L1." (PMID 32012775, 2020). "On the other hand, encouraging evidence about the prognostic role of both IDO1 and PD-L1 in NSCLC has been found, as confirmed in the current study by the correlation between the IDO1 overexpression and the high probability of death from cancer." (PMID 32536910, 2020). "Human trials with IDO-1 inhibitors as cancer therapies have been disappointing without a clear reason." (PMID 32505212, 2020). "The discovery of IDO1 and HDAC1 dual inhibitors may provide a novel strategy for cancer treatment by taking advantages of both immunotherapeutic and epigenetic drugs." (PMID 33007982, 2020). "In contrast to IDO1, little is known about the regulation of TDO2 in cancer." (PMID 32477324, 2020). "High IDO1 expression has been shown to correlate with reduced levels of infiltrating CD3+ T cells, CD8+ T cells, CD57+ NK cells, B cells and increased levels of forkhead box P3 (Foxp3)+ Tregs48–52 in different cancer types." (PMID 31819194, 2020). "Because of the different roles of IDO1 and TDO in cancer, it is unlikely that TDO expression may have compensated for IDO1 inhibition in the ECHO-301/KEYNOTE-252 trial." (PMID 33584686, 2020). "This was decided based on allometric scaling indicating that NTRC 3883-0 is unlikely to reach sufficient target coverage of human IDO1 at acceptable dose levels in cancer patients." (PMID 33584686, 2020). "Also of notice, a pronounced number of critical immunomodulators, which were described in an immunogenomic analysis of major TCGA cancer data sets and included PDCD1LG2, BTN3A2, GZMA, BTLA, CD28, ICOS, and IDO1, were contained in the 358 DEG set." (PMID 32603365, 2020). "Thus far, only a few cancer cell lines that express TDO constitutively are known, while many cell lines express IDO1 upon stimulation with IFNγ." (PMID 33584686, 2020). "Seeing that IDO1 inhibitors are promising for BC treatment and that MT can activate AHR, a transcription factor involved in the progression of some types of cancer, we have raised the possibility that MT activates AHR in BC cells, pointing it as inadequate to treat this type of cancer." (PMID 32907554, 2020). "According to a previous study, IDO1 promotes cancer cell proliferation independent of its ability to limit T cell-mediated immune surveillance." (PMID 31514488, 2019). "These trials included mainly ICIs, but also immunostimulatory antibodies, anti-cancer vaccines, oncolytic viruses, TLR agonists, indoleamine 2,3-dioxygenase 1 (IDO1) inhibitors, recombinant cytokines, adoptively transferred cells, and several small molecules with immunostimulatory effects." (PMID 31179236, 2019). "Notch3 silencing in MCF7 and TFK1 cells results in Mdh1, Idh1 and Ido1 down-representation, as observed in HepG2 and Huh7 HCC cell lines, suggesting that Notch3 regulation of metabolic pathways is a common feature in different human cancer cells." (PMID 30765875, 2019). "The novel findings suggested that both IDO1 and COL12A1 may be promising targets on anti-cancer treatment in GC." (PMID 31315643, 2019). "Therefore, miR-153 and IDO1 are suitable adjunct drug targets, e.g., in combination with CAR T cells, for adequately unleashing the immune response against cancer." (PMID 29685162, 2018).